HIF1A (hypoxia inducible factor 1 subunit alpha)
Diseases named in the same sentence as HIF1A in open-access papers (continued):
Sharing a sentence is not in itself a finding about the gene and the disease.
preeclampsia (continued). "The two genes, hif1α and TGFβ3 are overexpressed in pregnancies complicated by preeclampsia and IUGR." (PMID 22615960, 2012). "Our previous findings of placental hypoxia in preeclampsia together with the present data on disruption of oxygen sensing mechanisms explain the elevated HIF-1α levels found in preeclamptic placenta." (PMID 20967267, 2010). "Since hypoxia, or more generally brutal variation in oxygen pressure, are considered as major actors of preeclampsia pathogenesis, it was interesting to match the microarray result with HIF1α induction." (PMID 19079545, 2008). "Based on the cell proliferation or viability assay results, metformin, aspirin, resveratrol, or AD-01 may be useful for prevention of preeclampsia by reversing HIF-1α or oxidative stress-induced first trimester trophoblast cell damage." (PMID 40109359, 2025). "In addition, miR-20a and miR-20b were observed to be upregulated in preeclampsia in placental tissue and function in conjunction to downregulate HIF-1α." (PMID 41361850, 2025). "However, the promoter binds the E2F4 transcription repressor, which is upregulated in preeclampsia via the activated HIF1A/TGFB3 axis." (PMID 41167398, 2025). "Furthermore, sFLT1 expression has been reduced in this experimental setting which also contributes to the fact that HIF1A can upregulate this anti-angiogenic factor in human preeclampsia as well." (PMID 41020802, 2025). "Elevated levels of HIF-1α have also been observed in patients with preeclampsia." (PMID 40917787, 2025). "The detection of HIF-1α and its direct signaling partner microRNA-210 (miR-210) within systemic maternal sEVs lays the groundwork for identifying how sEV signaling contributes to the development of preeclampsia." (PMID 38777947, 2024). "High regulation of HIF-1α oxygen resulting from preeclampsia has been shown to be a critical determinant of placentagenesis and plays an important role in placental differentiation, changes in maternal and fetal blood circulation, trophoblastic invasion, and syncytial node increase." (PMID 37194760, 2023). "Furthermore, HIF1A induces the expression of soluble vascular endothelial growth factor receptor-1 (sFLT-1), a key factor in preeclampsia." (PMID 37759628, 2023). "Levels of HIF-1α increase in preeclamptic placentas, in placentas from human high-altitude pregnancy, in uterine arteries of high-altitude acclimatized pregnant sheep, and in placentas of a hypoxic rodent model of preeclampsia." (PMID 36674858, 2023). "Considering the species specificity of preeclampsia and the high conservation of HIF1α in virtually all mammals, we speculated that the presence of species-specific molecules may initiate and regulate this mechanism." (PMID 36160709, 2022). "However, the subgroup analyses of autoimmune diseases, inflammation, preeclampsia, CVD, T2D and other showed insignificant association with the HIF1A 1772 C/T polymorphism." (PMID 35972942, 2022). "Furthermore, there is evidence that preeclampsia induced maternal cardiac hypoxia as the protein levels of HIF-1α are increased compared to the sham controls in agreement with the altered carbohydrate pool." (PMID 35064159, 2022). "Therefore, this study provides an evolutionary perspective and insights into the pathogenesis of preeclampsia, namely, HIF1α/UCA1-induced adaptive responses that link the placental hypoxia adaptation to distant endothelial injury." (PMID 36160709, 2022). "We also measured the levels of HIF1α and HIF2α proteins, which are upregulated during ischemia and have previously been reported to be an important trigger for the upregulation of sFLT1 during preeclampsia." (PMID 35943814, 2022). "In the present study, we reported that urothelial cancer associated 1 (UCA1), a hypoxia-responsive long noncoding RNA (lncRNA), was a potentially critical mediator linking the HIF1α-induced placental hypoxia adaptation to distal maternal endothelial injury, leading to the occurrence of preeclampsia." (PMID 36160709, 2022).
preeclampsia (continued). "HIF-1α may be a marker of late-onset preeclampsia as HIF-1α has been described as a marker of cardiovascular disease." (PMID 33758274, 2021). "The median (IQR) serum HIF-1α levels of overall preeclampsia and late-onset preeclampsia were 1315.2 (645.9, 5128.7), and 1715.5 (852, 5134) pg/ml, respectively, which were significantly higher than that of normal pregnant women (699.5 (426.8, 1107.1) pg/ml) (p < 0.001, and < 0.001, respectively)." (PMID 33758274, 2021). "Therefore, the efficacy of using maternal serum level of HIF-1α as a predictive marker for preeclampsia has been questioned." (PMID 34681861, 2021). "When a combination of abnormal serum HIF-1α levels and abnormal uterine artery Doppler PI (above the 95th percentile) were used as a predictive value to predict preeclampsia, the sensitivity, specificity, PPV, and NPV were 74.2%, 67.2%, 16.6%, and 96.8%, respectively." (PMID 33758274, 2021). "RUPP animals show the clinical symptoms of preeclampsia during late gestation along with increased levels of hypoxia inducible factor (HIF)-1α, a cellular transcription regulator which responds to local oxygen levels to control vascularization and angiogenesis." (PMID 30679723, 2019). "HIF-1α expression remains elevated in preeclampsia, which may contribute to continued shallow trophoblast invasion and reduced placental perfusion." (PMID 30679723, 2019). "However, in placentas of pregnancies complicated by preeclampsia, low oxygen triggers a hypoxic response, which leads to an elevation of HIF-1α, a consequent reduction in trophoblast invasion, and placental hypoperfusion." (PMID 31316078, 2019). "Interestingly and in accordance with the role of hypoxia in preeclampsia, HIF1A can regulate the expression of several top DEGs identified in the meta-analysis including: LEP, FLT1, INHA, BHLHE40, SPAG4, HK2, HILPDA and ERO1L." (PMID 27802351, 2016). "Finally 2ME ameliorates the restricted trophoblast invasion in preeclampsia via suppression of HIF-1α." (PMID 26000015, 2015). "Since preeclamptic placentas are characterized by increased oxidative stress, over-expression of active HIF-1α and 2-α and reduced activity of proteasomal proteins, an up-regulation of Snail in human preeclampsia might be suggested." (PMID 22360878, 2012). "The frequency of the C1772T and G1790A polymorphisms of the HIF1A gene is very low, and neither polymorphism is associated with the development of preeclampsia in the Mexican population." (PMID 21414224, 2011). "HIF-1α expression was next examined in placentae from late-onset preeclampsia." (PMID 20967267, 2010). "Of clinical significance, we found that HIF-1α hydroxylation is markedly reduced in preeclampsia." (PMID 20967267, 2010). "Herein, we examined whether dysregulation of the oxygen sensing mechanism and consequently, HIF-1α stability, may be responsible for the increased HIF-1α levels in preeclampsia." (PMID 20967267, 2010). "With regard to pathology, preeclampsia is widely understood to feature inadequate remodeling of maternal arterioles and concomitant reduced blood and oxygen availability for the placenta, and higher levels of HIF-1α and/or HIF-2α protein have been observed in preeclamptic placenta." (PMID 40280139, 2025). "Therefore, human-specific molecules should link increased HIF1α to preeclampsia." (PMID 36160709, 2022). "Therefore, this study assessed the predictive value of serum HIF-1α combined with uterine artery Doppler in singleton pregnancy during 11–13+6 weeks of gestation for preeclampsia and other pregnancy complications, such as fetal growth restriction, preterm delivery, and perinatal death." (PMID 33758274, 2021). "Therefore, we propose that HIF1α and autophagy inhibition may create a vicious cycle in the progression and manifestation of preeclampsia." (PMID 24098539, 2013).
preeclampsia (continued). "Our findings indicate that HIF-1α and BNIP3, as well as its mediated mitophagy, are upregulated in the placentas of pregnant women with preeclampsia (PE), as well as in a PE-like mouse model." (PMID 40242759, 2025). "Hif-1α and SOX9 proteins can be used as a marker to show severity of preeclampsia and regulation of cell proliferation and angiogenesis during placental development." (PMID 37878989, 2023). "Placental hypoxia apparently persists beyond the first trimester in preeclampsia and FGR as HIF-1α and HIF-2α expression in the placenta keeps elevated throughout pregnancy." (PMID 33800426, 2021). "This manifests in clinical preeclampsia in humans and leads to the activation of RAS and the placental inflammatory mediators Hif1a and Ptgs2." (PMID 34959804, 2021). "HIF expression is shown to be higher in normal pregnancy, probably due to high estrogen and progesterone levels; however, HIF-1α and HIF-2α is overexpressed further in preeclampsia in response to RUPP." (PMID 34681861, 2021). "The prolonged status of placental hypoxia in both, preeclampsia and IDAP, increases the accumulation of the α subunit of the transcriptional factor induced by hypoxia (HIF-1α)." (PMID 30854239, 2019). "In preeclampsia, it is possible that decreased SPHK1 levels lead to persistent HIF1A stabilization and activity." (PMID 27284992, 2016). "In preeclampsia group, HIF expression was observed as clusters in the fibroid structures inside the chorionic villi and positive HIF expression in the syncytial nodes –HIF-1α immunostaining, bar: 200 μm, magnification: 20X." (PMID 37194760, 2023). "In contrast to mice with global Phd2 deficiency, the placental (conditional) Phd2 knockout (Phd2–/– cKO) is not embryonically lethal, making it a suitable preeclampsia model for examining anti-HIF-1A therapy." (PMID 36227697, 2022). "Hypoxia is a characteristic feature of preeclampsia; trophoblasts highly express FSTL3 after using hypoxia-mimetic agents, and hypoxia-inducible factor-1 alpha (HIF1α) may be involved in promoting FSTL3 expression." (PMID 36325361, 2022). "The serum HIF-1α levels with or without the uterine artery Doppler at 11–13+6 weeks of gestation were effective in predicting preeclampsia." (PMID 33758274, 2021). "This study found that the serum HIF-1α levels with or without the uterine artery Doppler in the first trimester was effective in predicting preeclampsia." (PMID 33758274, 2021). "This study showed that the serum HIF-1α levels with or without uterine artery Doppler at 11–13+6 weeks of gestation were effective in predicting preeclampsia." (PMID 33758274, 2021). "Regarding first trimester angiogenic factors and HIF-1α in preeclampsia, there has been no study to evaluate first trimester angiogenic factors as their expression is enhanced by increased HIF-1α." (PMID 33758274, 2021). "The sensitivity of serum HIF-1α levels with or without the uterine artery Doppler in predicting preeclampsia were 74.2% and 66.7%, respectively." (PMID 33758274, 2021). "HIF-1α (in hypoxic conditions) has been shown to increase VEGFA expression, while a reduction in VEGF has been observed in placentae from complicated pregnancies such as preeclampsia." (PMID 31178743, 2019). "Notably, it has experimentally validated interactions with a number of genes known to be directly involved in the pathology of preeclampsia, particularly at the placenta: VEGF, NOTCH-3, IGF-1 and hypoxia inducible factor 1 α (HIF-1α)." (PMID 26213997, 2015). "2ME has been shown to ameliorate all preeclampsia-like features without toxicity in Comt(−/−) pregnant mice and to suppress placental hypoxia, HIF-1α expression, and increased sFLT-1 expression." (PMID 26000015, 2015).
preeclampsia (continued). "In the trophoblast of women with preeclampsia, hypoxia-inducible factor 1 alpha (HIF-1α) is over-expressed, and induces the expression of non-angiogenic factors and inhibitors of trophoblast differentiation." (PMID 21414224, 2011). "Therefore, Hif-1α signal and SOX9 transformation factor may play an important role in determining the severity of preeclampsia and also in the regulation of cell proliferation and angiogenesis." (PMID 37878989, 2023). "In the present study, the expression of human-specific UCA1 showed the same change as HIF1α expression in normal pregnancy and preeclampsia: high expression in early gestation that dwindled during normal pregnancy but was upregulated in the preeclamptic placenta again." (PMID 36160709, 2022). "Serum HIF-1α levels have never been used to predict preeclampsia." (PMID 33758274, 2021). "However, the median (IQR) serum HIF-1α level of early-onset preeclampsia was 646.7 (438.9, 5151.9) pg/ml which was not different compared to the controls (p = 0.629)." (PMID 33758274, 2021). "Moreover, HIF-1α upregulates anti-angiogenic factors such as sFlt-1, sEng, and ET-1 expressions and AngII and AngII-converting enzyme (ACE) expressions in the lungs and kidney which add on to the abnormal placentation and development of preeclampsia." (PMID 34681861, 2021). "The use of advanced techniques in combination with preexisting comorbidity models, such as trophoblast-specific gene transfer of HIF-1α in mice on a high fat Western diet or sFLT1 in non-obese diabetic mice, may more accurately reflect preeclampsia superimposed on a comorbidity." (PMID 37089425, 2023). "Given that DMOG is extensively known as HIF-1α mimic, we did not measure HIF-1α expression in trophoblast cells, however we demonstrated increased expression of oxidative stress biomarkers, UA and MDA, which are the most relevant to preeclampsia, in DMOG-treated trophoblasts." (PMID 40109359, 2025).
Hypertension (73 papers, 2010 to 2026). The presence of chronic increased pressure in the systemic arterial system. "Multivariate logistic analysis identified smoking, higher Global Initiative for Chronic Obstructive Lung Disease grade, hypertension, and elevated levels of HIF-1α, ET-1, and NO as independent risk factors for AECOPD." (PMID 39412137, 2025). "We evaluated the putative association between polymorphisms and haplotypes in parental and child HIF-1α genes and the risk of severe-spectrum hypertensive disorders of pregnancy." (PMID 40085397, 2025). "We conclude that polymorphism changes and haplotypes in the HIF-1α gene of mothers, fathers, and children are associated with risk for severe-spectrum hypertensive disorders of pregnancy." (PMID 40085397, 2025). "To elucidate the functional role of HIF-1α in the pathogenesis of hypertension associated with SAS, we administered siRNA targeting HIF-1α to rats prior to exposure to CIH conditions." (PMID 39732653, 2024). "This study shows that the activation of the ET system, facilitated by HIF-1α activity, is the cause of the increased vulnerability to IH and the resulting cardiovascular effects, such as hypertension and ischemic damage." (PMID 38276286, 2024). "These ROS, in combination with low oxygen levels, function together to stimulate the upregulation of HIF-1α and contribute to the development of hypertension caused by IH." (PMID 38276286, 2024). "Changes in several genes, including JAK2, PTGS2, and HIF1A, which have also been connected to the emergence of hypertension, have been linked to resistance to these inhibitors." (PMID 37571339, 2023). "The emergence and progression of hypertension have been linked to the genes HIF1A, CYP11B1, and NR3C1." (PMID 37571339, 2023). "HIF-1α may play a role in the development of hypertension caused by IH by increasing the expression of ET-1." (PMID 38276286, 2024). "Thus, this study provides compelling evidence supporting a strong causative role for VSMC HIF1α and M1 macrophage infiltration in the pathogenesis of arterial hypertension and vascular remodeling." (PMID 31320613, 2019). "HIF1A expression levels are acknowledged for contributing to the regulation of vascular smooth muscle tone and low levels of HIF1A expression have been shown to be associated with hypertension due to hypercontractile vascular smooth musculature." (PMID 30455683, 2018). "HIF-1a, is also associated co morbidities such as hypertension and hyperlipidaemia." (PMID 20942928, 2010). "Additionally, it has been reported that MC-LR could down-regulate VEGFA and TGF-β expression via the AKT/m-TOR/HIF-1α pathway, which was linked to hypertension." (PMID 39728800, 2024). "Several genes are associated with vascular disease and hypertension during pregnancy via impaired inflammatory response, hypoxia, and oxidative stress, such as cytokines/chemokines IL-1β, IL-6, IL-8, and impairment expression in endothelial cells/VSMCs of HIF1α and eNOS genes." (PMID 34867473, 2021). "Furthermore, impaired HIF-1α serum levels have been implicated in a circadian clock disruption and as a mediator of insulin resistance, type 2 diabetes and consequently of diabetes-related hypertension." (PMID 33669062, 2021). "With prolonged treatment (4 weeks), these differences were lost, suggesting a protective role for myeloid HIF-1α only in early hypertension-induced cardiac hypertrophy." (PMID 41525184, 2026). "Hypoxia-inducible factor 1-alpha (HIF-1α), often upregulated in sarcomas, is also linked to both VEGF expression and systemic hypertension." (PMID 40564764, 2025). "In diabetes, hyperglycemia stabilizes HIF-1α, while hypertension promotes VEGF expression through Ang II–driven AP-1 activation." (PMID 41164182, 2025). "Repeated apnea leads to CIH-induced HIF-1α upregulation and increased ROS production, thus promoting the occurrence of hypertension." (PMID 39732653, 2024).